MTOR (mechanistic target of rapamycin kinase)
Diseases named in the same sentence as MTOR in open-access papers (continued):
Sharing a sentence is not in itself a finding about the gene and the disease.
tumor (continued). "Unfortunately, clinical outcomes after treatment with agents such as tyrosine kinase inhibitors (TKIs) and mammalian target of rapamycin (mTOR) inhibitors have not shown satisfactory improvement due to tumour recurrence and metastasis." (PMID 31138790, 2019). "Besides, mTOR inhibition can also act synergistically with radiation therapy to reinforce the anti-angiogenic effects and suppress HNSCC tumor growth in xenograft models." (PMID 30754640, 2019). "Besides, endocrine resistance and tumor progression are induced at the result of abnormal activation of several growth factors signaling pathways, especially the PI3K/Akt/mTOR pathway." (PMID 31557936, 2019). "We also sought to determine whether modulation of the Akt/mTOR signaling pathway, in particular by CTC, could mediate its anti-neoplastic actions against tumor cells." (PMID 30813295, 2019). "We found that these agents inhibited the mTOR(Mechamistic\Mammilian Target of Rapamycin) pathway in tumor cells growing under glucose starvation, but not under normal conditions." (PMID 30704052, 2019). "Immunotherapeutic approaches using ex vivo cultures for adoptive transfer of genetically modified T-cells including tumor-infiltrating lymphocytes and chimeric antigen receptor-T cells (CAR-T) could also be enhanced by manipulation of mTOR activity." (PMID 31817676, 2019). "Based on the quantitative data as well as the landscape masks provided by Spa-RQ analysis, we observed a phenotype of stromal MAPK signature in conjunction with tumour-specific mTOR signalling, in both ‘MAPK/mTOR’ (ASC_12, 13) and ‘Null’ (ASC_5) signature ASCs." (PMID 31772293, 2019). "A similar regression of the tumours was observed after treatment of mice with the dual PI3K/mTOR inhibitor NVP-BEZ235 but not with the mTOR inhibitor rapamycin." (PMID 31018529, 2019). "Hypoxia effect on tumor malignancy involves hypoxia-inducible factors, stem population, negative modulation of apoptotic axis and molecular pathways related to regulation of cell metabolism including PI3K/AKT/mTOR pathway." (PMID 31214505, 2019). "Therefore, it is likely that the stromal cells secrete CCL5 into the tumor microenvironment and that CCL5, by binding to CCR5, activates the AKT/mTOR pathway and promotes tumor metastasis." (PMID 31500658, 2019). "We therefore applied Spa-RQ to investigate whether the classification of tumours based on MAPK/mTOR (OL; pERK/p4EBP1) or AKT/mTOR (OL; pAKT/p4EBP1) co-activation signatures translates to human samples." (PMID 31772293, 2019). "Moreover, due to numerous metabolic and tumor studies, it was our expectation that APN absence would coincide with active AMPK/mTOR signaling in APN KO HCCs." (PMID 30794695, 2019). "Therefore, several key factor in the downregulation of mTOR signaling, like the TSC complex, have been described as tumor suppressors." (PMID 30609721, 2019). "mammalian target of rapamycin (mTOR) inhibitors and anti-VEGF may act as regulators of tumor-specific and allogenic T-cells." (PMID 31058839, 2019). "We need to further study the relationship between CD73, mTOR, and autophagy, which may contribute to understanding why the anti-CD73 antibody enhances chemosensitivity and inhibits tumor metastases." (PMID 30823477, 2019). "In this study, DLD-1R and HCT-116R cells appeared to be sensitive towards regorafenib treatment as demonstrated by the decreased number of colonies, tumor spheres and stem-like phenotypes (tumor spheres and side-populations) and markers (WNT1, mTOR/STAT3, Notch1)." (PMID 30005681, 2018). "While tumor cells can adapt and survive when either single pathway is inhibited, combined inhibition of PI3K/AKT and AR signaling using the PI3K/mTOR inhibitor BEZ235 and the AR antagonist enzalutamide (ENZ) significantly delayed castrate‐resistant LNCaP tumor progression." (PMID 29572264, 2018). "Interestingly, we also focus on mTOR inhibitors and MDA19 comparison and even combination on effect of OS tumor properties in the further work." (PMID 30442873, 2018).
tumor (continued). "Importantly, C800 inhibited the phosphorylation of the Akt/mTOR, MAPK, and NF-κB pathways, which are responsible for tumor relapse and metastasis, leading to programmed cell death in T11 and SUM159PT TNBC cells." (PMID 29419736, 2018). "Endurance and, to a lesser extent, resistance exercise represent a significant metabolic stress, activating AMPK and thus inhibiting mTOR also in nonmuscular tissue such as liver, fat, and tumor tissues." (PMID 30363988, 2018). "FGFR1 controls glucose uptake and utilization by activating the AKT/mTOR pathway, which in turn in involved in the induction of GLUT-1 glucose transporter expression; FGFR inhibitors exert their anti-tumor activity also through the inhibition of glucose metabolism through AKT/mTOR inhibition." (PMID 30060526, 2018). "The AMPK/mTOR pathway is one of the most recognized anti-tumor mechanisms of metformin, so we next investigated whether AMPK/mTOR activation is involved in overcoming drug resistance." (PMID 29416762, 2018). "Major survival pathways and their aberrant activation have been reported to frequently occur and contribute towards the development and progression of tumor growth, including the PI3K (phosphatidylinositol 3-kinase)/AKT (protein kinase B)/mTOR (mammalian target of rapamycin) signaling pathway." (PMID 29642900, 2018). "Furthermore, the effect of AAP-H on tumor growth and the role of the PI3K/AKT/mTOR signaling pathway in nude mouse model were also investigated." (PMID 30208576, 2018). "In addition, the loss-of-function studies with specific pharmacological inhibitors and lentivirus-based shRNAs further indicated that SALL1-mediaed tumor suppression and senescence induction is controlled by both MAPK and mTOR signaling pathways." (PMID 29625565, 2018). "We also provide evidence that Aspirin may suppress tumor growth by activation of AMPK and inhibition of mTOR signaling." (PMID 30042442, 2018). "Repeated biopsies of brain metastases showed that the tumor tissue contains EGFR suppressors, phosphoinositide 3-kinase (PI3K)/AKT/mammalian target of rapamycin (mTOR), mitogen-activated protein kinase (MAPK), and cyclin-dependent kinase pathways, and other potential targets." (PMID 29435193, 2018). "The SH2B1/Akt/mTOR/PTEN axis is required for regulating NSCLC cell proliferation and might prove to be a promising strategy for restraining tumor progression in NSCLC patients." (PMID 30202243, 2018). "Tumour masses from mice injected with UCP2 (genipin) and mTOR inhibitors (everolimus) revealed a strong reduction in tumour volume and number of mitosis, associated with a marked cytosolic glycolytic enzyme glyceraldehyde 3-phosphate dehydrogenase (GAPDH) nuclear positivity." (PMID 29587429, 2018). "Indeed, in response to oxygen and/or nutrient deprivation, mTOR stimulates tumor cells to secrete factors, such as VEGF, that recruit new vessel formation to support the tumor growth." (PMID 29351204, 2018). "Combining PI3K/mTOR inhibitors with AKT or PDK1 inhibitors suppressed this rephosphorylation, induced apoptosis, decreased colony formation, cell viability and growth of tumor xenografts." (PMID 29357370, 2018). "We are first to report that in PTSMTs, a non-canonical activation of WNT, independent of beta-catenin, drives tumor cell proliferation via MTOR/AKT1, MYC and Cyclin D2." (PMID 29881541, 2018). "Tumours with mutant PTEN status showed a non-significant increase in rates of progression when compared to non-PTEN mutant tumours after either VEGFR or MTOR inhibition in metastatic patients in the RECORD-3 trial." (PMID 30099580, 2018). "Phosphatase and tensin homolog (PTEN) acts as a tumor repressor through negative feedback of the phosphoinositide 3-kinase (PI3K)–Akt–mammalian target of rapamycin (mTOR) pathway." (PMID 30115834, 2018).
tumor (continued). "On this basis, we propose to investigate a therapeutic triad in order to target these three major tumor cell populations, i.e., cytotoxic drugs acting on differentiated, proliferating tumor cells; mTOR inhibitors inhibiting EMT induction; autosis inducers promoting death of autophagic tumor cells." (PMID 30013478, 2018). "More importantly, activated Akt could activate mTOR downstream genes p70S6K and 4E-BP1 to promote tumor cell proliferation, angiogenesis and metastasis." (PMID 29507684, 2018). "While hypoxia affects many aspects of tumor biology, the degree to which HIF-1, mTOR, and UPR pathways converge on autophagy to promote survival remains unclear." (PMID 30250843, 2018). "In addition, LAC117 decreased the expression of p-AKT and p- mTOR, downstream of the PI3K/AKT pathways in tumor tissues." (PMID 29739391, 2018). "At low concentrations, capsaicin favors EMT transition by inhibiting E-cadherin expression, sustains tumor cell migration by inducing over-expression of MMP2 and MMP9 and activates Akt/mTOR signaling pathway, molecular events that together enhance the migration and invasive potential of SW480 cells." (PMID 30487390, 2018). "In addition, CXCL12-dependent stimulation of CXCR4 on tumor cells has been shown to activate key downstream pathways including PI3K/AKT/mTOR and ERK1/2, which promote tumor cell survival proliferation, migration, and angiogenesis." (PMID 30257500, 2018). "mTOR inhibitors, such as rapamycin, BEZ235, and TAK228, and pharmacological ROS insults, such as buthionine sulphoximine, auranofin, and piperlongumine, overcame intrinsic radioresistance, leading to delayed tumor growth in different tumor models." (PMID 30337872, 2018). "A number of kinases, proto-oncogenes, and tumor-suppressor genes, including PI3K, PDK1, phosphatase and tensin homolog, Akt, TCL1, tuberous sclerosis complex 1/2 (TSC1/2), FOXO, mechanistic target of rapamycin (mTOR), or eukaryotic translation initiation factor 4E, are contained in this network." (PMID 29872222, 2018). "Although the EGFP+ tumor cells displayed robust mTOR phosphorylation, the mTOR inhibitor, rapamycin, did not strongly affect the CSC-associated CD24 and CD44 markers (data not shown)." (PMID 29510720, 2018). "However, combined inhibition of mTOR and MEK resulted in profound tumor regression which was sustained for the duration of treatment." (PMID 29872503, 2018). "Furthermore, the MCF-7 tumor from the control and 20(S)-PPD-treated mice were harvested, and immunohistochemistry analysis was used to assess the PI3K/AKT/mTOR pathway and apoptosis." (PMID 29614812, 2018). "It is thus possible, that guided by molecular characterization of tumor lesions, we could use PI3K, AKT or mTOR inhibitors to disrupt AKT/mTOR signaling and inhibit S6 and PRAS40 activities as an effective approach to treat HCC." (PMID 30112114, 2018). "Tumor cells are more sensitive to amino acid deprivation than normal cells; thus, glutamine restriction and/or transporter inhibition decrease mTOR activity." (PMID 30363988, 2018). "Our hypothesis was that simultaneous blocking of the mTOR and MAPK pathways upstream ERK pathway could increase gemcitabine's anti-tumor effect." (PMID 29963262, 2018). "We treated p18−/−;Brca1MGKO and SUM149 tumor cells with or without E2 and found that E2 stimulated expression of p-Akt, p-4Ebp1, p-mTor, and p-Gsk3β in all time points tested from 2 to 144 h." (PMID 29996906, 2018).
tumor (continued). "The mechanistic target of rapamycin (mTOR), an atypical Ser/Thr protein kinase, is a downstream effector protein of AKT, which regulates transcription and protein synthesis, and has an important influence on growth and proliferation of tumor cells." (PMID 30497511, 2018). "Moreover, PI-3K, a regulator of Akt, is also deactivated by SEMA3F in tumor and ECs, suggesting that SEMA3F is a powerfull inhibitor of the PI-3K-Akt-mTOR signaling pathway." (PMID 30532711, 2018). "MYO18B promoted tumor growth and migration via the activation of PI3K/AKT/mTOR signaling pathway." (PMID 30390677, 2018). "PTEN is a tumor suppressor gene involved in multiple biological processes of carcinogenesis, including regulation of cell growth, proliferation, angiogenesis, and apoptosis by dysregulation of the PI3K/AKT/mTOR pathway." (PMID 30233642, 2018). "One of the proposed mechanisms how tumor cells develop resistance to mTOR inhibition is through the mTOR-dependent negative feedback loop that acts to inhibit PI3K/AKT activity." (PMID 28616837, 2018). "Targeted NGS analysis of tumor DNA demonstrated significantly more frequent PIK3CA mutations and PI3K/AKT/mTOR pathway alterations in non-responders." (PMID 30305115, 2018). "We show that metformin exerts anti-tumor activity through variable mechanisms of action, some of which may be independent of its effects on cellular metabolism and the AMPK/mTOR pathway." (PMID 29765528, 2018). "Studies in cultured cells and zebrafish model show that UBTOR inhibits mTOR signaling by stabilizing the mTOR complex component DEPTOR, and ubtor gene disruption result in higher mTOR activity and aggravate HRAS(G12V) induced neoplasia in the zebrafish." (PMID 30080879, 2018). "The mTOR inhibitors sirolimus (P = 0.03) and temsirolimus (P = 0.004) show negative enrichment with the individual tumour sample signatures, but not with the tumour group or subtype signatures." (PMID 29588458, 2018). "The effect of TKI/EV combination on the PI3K/AKT/mTOR and Ras/MEK/ERK is confirmed by a significant decrease of the levels of pCreb, the transcription factor involved in their signalling to promote tumor growth, apoptotic resistance, angiogenesis, and distant metastasis." (PMID 30546834, 2018). "Furthermore in NPC, treatment with soluble LIFR, an antagonist of LIF or rapamycin, an mTOR inhibitor of LIF, was found to reduce cell survival and tumour growth following irradiation in-vitro and in-vivo." (PMID 30263091, 2018). "They found that while normal tissues had no positivity for all the proteins considered, none of the tumor samples was negative for mTOR, S6K, or 4EBP1 phosphorylation." (PMID 30662577, 2018). "Therefore, it has become the focus of research in tumor therapy to inhibit cell proliferation or promote apoptosis through inhibiting PI3K, Akt, mTOR, and related genes by gene knockout or small molecule drug intervention." (PMID 29874795, 2018). "These were age, tumor diameter, surgery, and CK7, Ki-67, PTEN, and MTOR protein expression." (PMID 30619768, 2018). "For example, non-tumorigenic (stromal) cells of the tumor microenvironment secrete MCP1 to activate the mTOR pathway in neighboring breast cancer cells." (PMID 29662490, 2018). "In addition to mTOR activation through PI3K-AKT, other signaling pathways have also been reported to induce EMT in tumor cells." (PMID 30013478, 2018). "Therefore, literatures have recommended mTOR inhibitors for TSC/LAM patients to control and reduce tumor size." (PMID 29668633, 2018). "Even if mTOR is a key regulator of HIF-1, the activation of other signaling pathways, which converge on the targets shared with the PI3K network, can also promote tumor angiogenesis." (PMID 30126252, 2018). "Indeed, our preclinical data presented here show that combination of the ALK inhibitor crizotinib and the mTOR inhibitor rapamycin results in rapid and robust abrogation of MPM tumor growth in vivo." (PMID 29755689, 2018).
tumor (continued). "Though it had been hypothesized FLCN protein had tumour suppressor properties and could be one of the major proteins regulating the mTOR pathway, only recently was FLCN established as a tumour suppressor gene that fits the classic two-hit model." (PMID 30326848, 2018). "In addition to the upregulation of Treg into tumor tissues, mTOR signaling stimulates also the infiltration of MDSCs, thus allowing for it to combine immunotherapy with PI3K-AKT-mTOR pathway inhibitors." (PMID 30126252, 2018). "Besides HIF-1α, several regulatory pathways are also known to be involved in the regulation of glucose metabolism in tumor cells, such as Myc, PI3K/Akt/mTOR and AMP-activated protein kinase (AMPK)." (PMID 28886081, 2017). "In addition, mTOR, a downstream effector of the PI3K/AKT pathway has been reported to affect tumor progression." (PMID 28367998, 2017). "By utilizing our approach, we were able to detect dysregulation of the major molecular processes involved in HNSCC tumorigenesis (such as those involving PI3K/AKT/mTOR, RAS/RAF/MAPK, JAK/STAT, WNT/β-catenin and TGFβ/SMAD signaling) in almost every OSCC tumor analyzed." (PMID 28580171, 2017). "Modulation of PD-L1 levels occurs via two major pathways, the intracellular (innate) signaling pathway mediated by PI3K/AKT/mTOR activation and/or the extracellular induced (adaptive) pathway mediated by IFNγ production by TILs and subsequent IFNGRs/JAK/STAT signaling in tumor cells." (PMID 28107186, 2017). "Multikinase inhibitors (MKI) and mammalian target of rapamycin (mTOR) inhibitors prolong progression-free (PFS) and overall survival (OS) in the treatment of metastatic renal cell carcinoma (mRCC) by reducing angiogenesis and tumor growth." (PMID 28796163, 2017). "The changes in miRNA expression after treatment with LY294002 or Rapamycin primarily reflect the oncogenic features of the PI3K/mTOR pathway in NHL cells with downregulation of the oncogenic miRNA21 and upregulation of the tumor suppressor miRNAs 133a, -133b and -138-1." (PMID 28724379, 2017). "mTOR is a key member of the PI3K/AKT axis of RTK signalling, so combining mTOR and RTK inhibition may reduce opportunities for tumor escape and therapeutic resistance." (PMID 27732970, 2017). "This leads to decreased mTOR activity, glycolytic capacity, interferon-γ (IFN-γ) production, and cytolytic activity via production of granzyme and perforin in T cells resulting in tumor progression." (PMID 28447025, 2017). "While regulation of cell proliferation is mostly mediated by activation of the p38- and MEK-driven MAPK signaling cascades, most of the published work suggests a more prominent role of AXL in the PI3K/AKT/mTOR and JAK/STAT pathways in tumor cell survival [1••, 2, 10, 64]." (PMID 28251492, 2017). "Tumor sections obtained from the mice after sorafenib-only treatment showed enhanced expression of p-S6RP, p-p70S6K and p-4EBP1 as a result of an activation of the mTOR pathway." (PMID 28903416, 2017). "He showed data highlighting the powerful efficacy of combined therapeutic inhibition, including an almost complete reduction in tumour volume by targeting MAPK/ERK kinase 1 (MEK), mammalian target of rapamycin (mTOR) and the insulin growth factor receptor (IGFR)." (PMID 28386299, 2017). "In this study, our aim was to identify molecular aberrations predictive for response to everolimus, an mTOR inhibitor, regardless of tumor type." (PMID 28903445, 2017). "In vitro and in vivo studies using LMS cell lines showed that BEZ235 has a significantly higher anti-tumor effect than either BKM120 or everolimus, resulting in a greater reduction in tumor growth and more pronounced inhibitory effects on mitotic activity and PI3K/AKT/mTOR signaling." (PMID 28002802, 2017).